PTX3 (pentraxin 3)
Diseases named in the same sentence as PTX3 in open-access papers (continued):
Sharing a sentence is not in itself a finding about the gene and the disease.
thyroid (2 papers, 2023 to 2025). "The involvement of PTX3 in the regulation of immune responses, tissue remodeling and oncosuppressive processes led us to explore its potential role in the development of thyroid disorders." (PMID 37025408, 2023). "A preliminary analysis revealed that preoperative plasmatic PTX3 levels were significantly higher than normal in patients with thyroid disease (p<0.05)." (PMID 37025408, 2023). "Different patterns of expression could represent different mechanism of actions of PTX3 in the etiopathogenesis of thyroid disorders." (PMID 37025408, 2023). "PTX3 is a key component of the humoral arm of innate immunity regulating immune responses, tissue remodeling and oncosuppressive processes, all potentially involved in the development of thyroid diseases." (PMID 37025408, 2023). "Tissue analysis showed strong PTX3 expression in three of four ATC cases in tumor and stromal cells, whereas benign and differentiated thyroid tissues exhibited minimal staining." (PMID 41373493, 2025).
acute graft versus host disease (1 paper, 2022). A syndrome of immunologically mediated tissue damage that may occur following an allogeneic transplant, usually affecting the skin, liver, and GI tract. "The independent risk factors for IFD were grades 3–4 acute graft-versus-host disease, cytomegalovirus reactivation, and recipient and donor rs2305619 (PTX3) (P < 0.05) in multivariate analysis." (PMID 35346077, 2022).
acute leukemia (1 paper, 2021). A clonal (malignant) hematopoietic disorder with an acute onset, affecting the bone marrow and the peripheral blood. "However, it was showed that PTX3 genetic variants rs2305619 and rs3816527 were associated with invasive mold infections in acute leukemia patients undergoing intense chemotherapy." (PMID 33967610, 2021).
adrenal adenomas (1 paper, 2018). "It was reported that serum PTX3 level in patients with adrenal adenomas was higher than that of in healthy controls and PTX3 was correlated with urinary metanephrine concentration." (PMID 29715313, 2018). "Furthermore, it was reported that PTX3 was increased in patients with adrenal adenoma." (PMID 29715313, 2018).
adrenal tumour (1 paper, 2024). "Among the pathogenic elements of these cardio-metabolic elements, new emergent biomarkers are mandatory, as recently proven by a higher level of pentraxin 3, an acute-phase glycoprotein that has been involved in this particular instance of adrenal tumour-related cardio-metabolic traits." (PMID 39062179, 2024).
airways allergies (1 paper, 2023). "There are previous studies that propose a protective role for Pentraxin 3 and MIP-3b in airways allergies." (PMID 38139075, 2023).
allergic rhinitis (1 paper, 2020). Inflammation of the nasal mucous membranes caused by an IgE-mediated response to external allergens. "Children monosensitized to seasonal or perennial allergens and those with allergic rhinitis presented higher PTX3 plasma levels which also correlated with symptom severity." (PMID 32246830, 2020). "Notably, there is also a role for PTX3 in children with allergic rhinitis." (PMID 32246830, 2020).
anaphylaxis (1 paper, 2023). An acute hypersensitivity reaction that occurs from exposure to an allergen. "Of these, we identified one biomarker that is of high importance (IL-1B), and three others (MIP-3b, TWEAK R, and Pentraxin 3) that were of critical importance during anaphylaxis." (PMID 38139075, 2023).
aortic aneurysm (1 paper, 2022). A ruptured aneurysm located in the wall of the proximal portion of the descending aorta proceeding from the arch of the aorta. "Both MMP-9 and PTX3 could be of relevance for the pathogenesis of aortic aneurysms, potentially through interacting mechanisms." (PMID 36606286, 2022).
apical periodontitis (1 paper, 2022). "This indicates that system inflammatory burden of PTX-3 can be raised in patients with apical periodontitis, whereas endodontic treatment has a positive effect of on PTX-3 serum inflammatory levels." (PMID 35888650, 2022).
Ascites (1 paper, 2020). Accumulation of fluid in the peritoneal cavity (between the layers of the peritoneum that lines the abdomen). "PTX3 was, nevertheless, higher in patients with variceal bleeding compared to those with refractory ascites." (PMID 32078718, 2020). "Moreover, PTX3 levels were not induced in patients presenting with ascites or grades III/IV encephalopathy." (PMID 32078718, 2020).
autoimmune encephalitis (1 paper, 2022). Inflammation of the brain secondary to an immune response triggered by the body itself. "According to recently published research, patients with NMDAR antibody-associated autoimmune encephalitis had increased IL-6, pentraxin-3, CD40L, and IL-17A in their CSF." (PMID 36048783, 2022).
bladder tumour (1 paper, 2024). "These patients had undergone a transurethral resection of a bladder tumour (TURBT) before inclusion, which could have had an effect on plasma levels of PTX3." (PMID 38542446, 2024).
bone cancer (1 paper, 2022). A primary or metastatic malignant neoplasm affecting the bone or articular cartilage. "Moreover, further studies are required to examine whether the pentraxin-3 and nectin-1 cascade in the spinal dorsal horn is implicated in other pain syndromes, such as inflammatory pain, bone cancer pain, chemotherapy-induced neuropathy and opioid-induced hyperalgesia." (PMID 35625034, 2022).
breast cancer disease (1 paper, 2020). "Recently, PTX3 was seen to be involved in the ectopic calcifications’ formation in breast cancer disease." (PMID 33584725, 2020).
bronchiectasis (1 paper, 2017). Segmental, irreversible dilation of the bronchial tree resulting in the accumulation of secretions which leads to obstruction. "First, we did not have data on PTX3 in healthy controls, which would support whether levels detected in the COPD population are elevated; an additional infection control, such as bronchiectasis, would provide added value." (PMID 28458531, 2017).
bronchopneumonia (1 paper, 2021). Acute inflammation of the walls of the terminal bronchioles that spreads into the peribronchial alveoli and alveolar ducts. "Ptx3-/- mice developed multifocal areas of fibrinosuppurative and necrotizing and/or haemorrhagic bronchopneumonia, and the infection diffused to the perivascular interstitium, compared with milder tissue damage and confinement of bacteria in the bronchial and alveolar spaces of wild-type mice." (PMID 34093560, 2021).
Burkholderia Infections (1 paper, 2019). Infections with bacteria of the genus BURKHOLDERIA. "In addition to investigating the role of PTX3 in the pathogenesis of Bm infection, this genome-wide transcriptome study has identified several modulated genes and pathways that can be further investigated for their potential relevance as immunotherapeutics during Burkholderia infection." (PMID 31492148, 2019).
Cachexia (1 paper, 2023). Severe weight loss, wasting of muscle, loss of appetite, and general debility related to a chronic disease. "Analyzing the soluble immune mediators associated with cachexia, the combination of cachexia and PTX‐3 or OPN expression levels was predictive for PFS and the combination of cachexia and CRP or OPN expression levels was predictive for OS." (PMID 37712645, 2023). "We have shown that CRP and PTX3 may be associated with cachexia." (PMID 37712645, 2023). "There were significant differences in PFS for the combination of cachexia and PTX‐3 (p = 0.008, log‐rank) or OPN (p = 0.030, log‐rank) expression levels." (PMID 37712645, 2023). "Among the soluble immune mediators we detected that were associated with cachexia, the combination of cachexia and CRP, PTX‐3, or OPN expression levels were each associated with patient prognosis." (PMID 37712645, 2023). "Logistic regression analysis identified ghrelin, c‐reactive protein (CRP), pentraxin‐3 (PTX‐3), and osteopontin (OPN) as factors associated with cachexia." (PMID 37712645, 2023). "Pre‐treatment ghrelin, CRP, PTX‐3, and OPN may be associated with cachexia in NSCLC receiving PD‐1 inhibitors." (PMID 37712645, 2023). "Pre‐treatment ghrelin, CRP, PTX‐3, and OPN may be associated with cachexia." (PMID 37712645, 2023). "Pre‐treatment ghrelin, CRP, PTX‐3, and OPN expression levels may be associated with cachexia." (PMID 37712645, 2023). "We found that ghrelin, CRP, PTX‐3, and OPN expression levels may be associated with cachexia." (PMID 37712645, 2023). "In the cachexia group, the median levels were 173.1 pg/mL, 1.63 pg/mL, 51,255.8 pg/mL, and 110,010.3 pg/mL for ghrelin, CRP, PTX‐3, and OPN, respectively." (PMID 37712645, 2023). "Although confirmation of our data in further large‐scale studies is needed, given the small sample size in this study, our study showed that CRP, PTX‐3, and OPN expression levels might serve as prognostic factors in patients with cachexia." (PMID 37712645, 2023). "The combinations of cachexia and CRP, PTX‐3, or OPN might serve as predictors of survival in patients with NSCLC receiving immunotherapy." (PMID 37712645, 2023). "Patients with NSCLC and cachexia who received PD‐1/L1 monotherapy tended to have worse survival than those without cachexia irrespective of presence of ghrelin, CRP, PTX‐3, and OPN." (PMID 37712645, 2023).
cardiac hypertrophy (1 paper, 2013). "This study aimed to examine the influence of PTX3 on cardiac hypertrophy and left ventricular dysfunction with respect to pressure overload." (PMID 23372656, 2013). "In the present study, cardiac hypertrophy was significantly attenuated in PTX3-KO mice than in WT mice at 2 weeks after TAC operation, however, fractional shorting was not change in this period." (PMID 23372656, 2013). "Furthermore, we demonstrated that cardiac hypertrophy, fibrosis, and dysfunction after pressure overload were significantly attenuated in PTX3-KO mice than in WT mice." (PMID 23372656, 2013). "IL-6 also activates ERK1/2 through the gp130 receptor and promotes cardiac hypertrophy, but inhibits cardiomyocyte apoptosis; increasing IL-6 levels may also accelerate the hypertrophic response in addition to the direct effect of PTX3." (PMID 23372656, 2013). "However, the effect of PTX3 on pressure overload–induced cardiac hypertrophy is unknown." (PMID 23372656, 2013).
colorectal polyps (1 paper, 2021). "In CRC, serum PTX-3 levels were significantly increased compared to healthy individuals or patients with colorectal polyps, representing an independent prognostic factor for CRC patients." (PMID 33776564, 2021).
colorectal tumor (1 paper, 2019). "Since epigenetic studies showed PTX3 silencing in colorectal tumor cells, increased PTX3 plasma levels in these patients reasonably reflect cancer-related inflammation associated with tumor growth." (PMID 31019517, 2019).
coxarthrosis (1 paper, 2025). "This pilot study aimed to investigate the effects of a cocktail with trolox, r-irisin and resveratrol on the metabolism of osteoblasts isolated from patients with coxarthrosis or fragility fracture by assessing the modulation of NOX4, SIRT1 and PTX3." (PMID 40956314, 2025).
Cushing syndrome (1 paper, 2021). Cushing's syndrome (CS) encompasses a group of hormonal disorders caused by prolonged and high exposure levels to glucocorticoids that can be of either endogenous (adrenal cortex production) or exogenous (iatrogenic) origin. "Interestingly, patients with Cushing syndrome had an increased circulating level of pentraxin-3, whereas pentraxin-3 levels were decreased in subjects affected by iatrogenic hypocortisolism." (PMID 35387000, 2021).
Dengue hemorrhagic fever (1 paper, 2021). A serious condition caused by Dengue virus infection. "Pentraxin-3 seemed to be an early prognostic indicator of disease severity in dengue hemorrhagic fever." (PMID 34001041, 2021).
diabetic macular edema (1 paper, 2024). "Furthermore, inflammatory factors sICAM-1, MCP1, and Pentraxin 3 (PTX3) are increased in the vitreous of patients with diabetic macular edema (DME), and steroids remain an effective alternative treatment to anti-VEGFs." (PMID 39348530, 2024). "Similarly, evaluation of a publicly available transcriptomic human dataset revealed increased PTX3 expression in DR with diabetic macular edema and proliferative retinopathy, when compared to nondiabetic retinas or diabetic retinas without complications." (PMID 39348530, 2024).
dilatation (1 paper, 2022). "All markers were associated with inflammation and the first two (i.e., PTX3 and resistin), in particular, were independent of cervical dilatation." (PMID 35536791, 2022).
Duchenne muscular dystrophy (1 paper, 2020). Duchenne muscular dystrophy (DMD) is a neuromuscular disease characterized by rapidly progressive muscle weakness and wasting due to degeneration of skeletal, smooth and cardiac muscle. "In this work, we wanted to investigate the predictive role of PTX3 in myocardial damage and fibrosis of Duchenne muscular dystrophy (DMD)." (PMID 32508664, 2020).
End Stage Liver Disease (1 paper, 2020). Final stage of a liver disease when the liver failure is irreversible and LIVER TRANSPLANTATION is needed. "In addition, PTX-3 levels are positively correlated with a model for end-stage liver disease and Child-Pugh scores in cirrhotic patients." (PMID 32915797, 2020).
eosinophilia (1 paper, 2021). "Interestingly, while the total inflammatory cells, BALF eosinophil and neutrophil counts and lung tissue eosinophilia were increased after allergen exposure irrespective of pentraxin-3 deletion, it was more prominent in pentraxin-3-/- mice." (PMID 35387000, 2021).
female infertility (1 paper, 2022). Diminished or absent ability of a female to achieve conception. "However, due to the female infertility of Ptx3 null mice and the early lethality of Galctwi/twi animals, the generation of double Ptx3−/−/Galctwi/twi mice would require a breeding program with a very large number of animals, incompatible with the rules of the local and national ethical committees." (PMID 36012705, 2022).
food allergy (1 paper, 2022). Gastrointestinal disturbances, skin eruptions, or shock due to allergic reactions to allergens in food. "However, the involvement of PTX3 in food allergy remains unknown." (PMID 36530573, 2022).
fungal meningitis (1 paper, 2022). Meningitis caused by fungal agents which may occur as opportunistic infections or arise in immunocompetent hosts. "C. neoformans treatment increased the expression of inflammation-related proteins, including pentraxin 3 (PTX-3), thrombospondin-1 (TSP-1), and IL-8, compared to C. glabrata infection, which does not commonly cause fungal meningitis." (PMID 35806421, 2022).
gingival fibromatosis (1 paper, 2021). "It is thus possible that low PTX3 amounts may influence progression of both gingival fibromatosis and inflammation." (PMID 34777248, 2021).
Gliosis (1 paper, 2022). Gliosis is the focal proliferation of glial cells in the central nervous system. "Here, immunohistochemical analysis demonstrated that autopsy brain specimens from Krabbe infants were characterized by an intense gliosis and PTX3 immunoreactivity that was detectable in macrophages and globoid cells, a hallmark of Krabbe disease." (PMID 36012705, 2022). "Here, we demonstrated that the soluble pattern recognition receptor PTX3 was expressed by monocyte-derived cells in brain specimens from Krabbe patients, its immunoreactivity being related to the extent of the pathology and gliosis." (PMID 36012705, 2022).
HCMV infection (1 paper, 2022). "We found that TOs secreted relatively few cytokines in response to HCMV infection, including pentraxin-3 (PTX3), first described as an endothelial factor induced by IL-1β treatment, IL-8, and IL-11." (PMID 35975985, 2022).
hepatitis B infection (1 paper, 2020). "Here, PTX3 was measured in serum of HCC patients where etiology was linked to NASH in 15 patients, hepatitis B infection in 3 patients, alcohol in 5 patients, and remained cryptic in 8 patients." (PMID 32078718, 2020).
hepatopathy (1 paper, 2013). "In contrast, serum PTX3 was significantly decreased in CF patients with hepatopathy." (PMID 23516586, 2013).
hip fracture (1 paper, 2025). Traumatic or pathological injury to the hip in which the continuity of either the femoral head, femoral neck, intertrochanteric or subtrochanteric regions is broken. "The acute phase protein PTX3 showed similar associations as those for SPP1, with higher hip fracture risk, lower BMD, higher bone turnover, and lower fat and lean mass." (PMID 39919333, 2025).
histoplasmosis (1 paper, 2025). A disease caused by the fungus Histoplasma capsulatum. "Elevated IL-1β, TNF- α, IL-18, and PTX3 levels in HIV patients with histoplasmosis could serve as a potential predictive biomarker for poor prognosis and disseminated disease development in these individuals." (PMID 40558960, 2025).
hyperopia (1 paper, 2016). A refractive error in which rays of light entering the eye parallel to the optic axis are brought to a focus behind the retina, as a result of the eyeball being too short from front to back. "Genes mediated by BMP signaling were also implicated, including HAS2 and PTX3 which were up-regulated during hyperopia induction and CTGF which was down-regulated during myopia induction." (PMID 27625591, 2016).
Hyperoxaluria (1 paper, 2018). Increased excretion of oxalates in the urine. "Despite the equal induction of hyperoxaluria in both genotypes, only the Ptx3-deficient mice developed a nephrocalcinosis." (PMID 30319631, 2018). "Thus, Ptx3-deficient mice display the full phenotype of hyperoxaluria-induced nephrocalcinosis and progressive CKD." (PMID 30319631, 2018). "We conclude that genetic factors control susceptibility for hyperoxaluria-related nephrocalcinosis and that PTX3 is an endogenous inhibitory factor preventing nephrocalcinosis and its deterious consequences, e.g., by limiting crystal growth and by induction of crystal adhesion molecules." (PMID 30319631, 2018). "Thereby PTX3 might limit nephrocalcinosis during hyperoxaluria, a hypothesis that is supported by the evidence presented and discussed in this study." (PMID 30319631, 2018). "Thus, renal tubular cells have the capacity to express PTX3 and secrete it into the urine, e.g., during hyperoxaluria." (PMID 30319631, 2018). "Having shown that PTX3 is present in the urine during hyperoxaluria, we sought to design an experiment that could examine its putative role as an inhibitor of CaOx crystallization." (PMID 30319631, 2018). "Furthermore, during hyperoxaluria in vivo renal tubular cells secrete PTX3 which serves as an endogenous inhibitor of intrarenal crystal aggregation and adhesion, nephrocalcinosis, kidney injury, and subsequent CKD." (PMID 30319631, 2018). "Therefore, the B6;129 mice were not susceptible per se to hyperoxaluria-induced nephrocalcinosis, however deletion of the ptx3 gene was sufficient to induce nephrocalcinosis in these animals, thus rendering them similar to other strains that are prone to nephrocalcinosis." (PMID 30319631, 2018).
iron deficiency (1 paper, 2021). "Patients with iron deficiency had significantly lower irisin and significantly lower PTX3 concentration." (PMID 34680053, 2021).
ischemia reperfusion injury (1 paper, 2019). Adverse functional, metabolic, or structural changes in ischemic tissues resulting from the restoration of blood flow to the tissue (reperfusion), including swelling; hemorrhage; necrosis; and damage from free radicals. "In murine models of ischemia-reperfusion injury both endogenous and exogenous PTX3 were described to alleviate leukocyte recruitment following renal ischemia, while the lack of PTX3 was associated with a higher degree of apoptosis and C3 deposition in damaged cardiac tissue." (PMID 30858847, 2019).